FGF2 (fibroblast growth factor 2)
Diseases named in the same sentence as FGF2 in open-access papers (continued):
Sharing a sentence is not in itself a finding about the gene and the disease.
epilepsy (7 papers, 2010 to 2024). A brain disorder characterized by episodes of abnormally increased neuronal discharge resulting in transient episodes of sensory or motor neurological dysfunction, or psychic dysfunction. "In addition to rodent studies, the implication of FGF2 has been investigated in human epilepsy-associated malformations of cortical development by autoptic analysis and corticectomy specimens." (PMID 24062643, 2013). "Our study suggests that the anti-inflammatory effect of BDNF and FGF-2 in vivo in the epilepsy model was indirect and likely due to a reduction in seizure frequency and severity." (PMID 38673746, 2024). "In an attempt to further elucidate the effect of FGF2 in epilepsy, we studied transgenic mice (TgFGF2) expressing the human FGF2." (PMID 24062643, 2013). "The data support the notion that FGF2 favors epilepsy development by altering gliogenesis and maturation of cortical neurons from migrating neuroblasts." (PMID 24062643, 2013). "Interestingly, it has been reported that Fgf2, Creb, and Ep300 are involved in pathogenesis of epilepsy which is susceptive in offspring from preeclamptic mothers." (PMID 25575681, 2016). "FGF2 exerts neuroprotective effects against a wide variety of insults, reducing brain cellular damage and improving functional recovery in experimental models of stroke, epilepsy, traumatic brain and spinal cord injury." (PMID 24062643, 2013). "And localized overexpression of Fgf2 could reduce epileptogenesis in an epilepsy rat model." (PMID 25575681, 2016). "We have previously reported that local, intrahippocampal supplementation of fibroblast growth factor-2 (FGF-2) and brain-derived neurotrophic factor (BDNF) increases neurogenesis, reduces neuronal loss, and reduces the occurrence of spontaneous seizures in a model of damage-associated epilepsy." (PMID 21087489, 2010). "In an in vivo model of epilepsy, the supplementation of brain-derived neurotropic factor (BDNF) and fibroblast growth factor-2 (FGF-2) using a Herpes-based vector reduced epileptogenesis-associated neuroinflammation." (PMID 38673746, 2024). "Localized delivery of FGF-2 and brain-derived neurotrophic factor (BDNF) to the lesioned hippocampus increases neurogenesis and reduces epileptogenesis in a rat model of epilepsy." (PMID 24735639, 2014). "Thus, it is tempting to hypothesize that the involvement in epilepsy of NTFs, specifically BDNF and FGF-2, could go beyond their well-known effects on cell death, neurogenesis, and axonal sprouting, but also include the control of neuroinflammation." (PMID 38673746, 2024).
esophageal squamous cell carcinoma (7 papers, 2019 to 2025). Esophageal squamous cell carcinoma (ESCC) is a type of esophageal carcinoma (EC) that can affect any part of the esophagus, but is usually located in the upper or middle third. "FGF2, regulating CSCs through Mek/Erk signaling, is an important factor in esophageal squamous cell carcinoma." (PMID 33381388, 2020). "FGF2 was indicated to regulate the FGFR-ERK signaling in esophageal squamous cell carcinoma to accelerate tumor growth." (PMID 30082912, 2019). "We can speculate that FGFBP1 may promote the development of esophageal squamous cell carcinoma through FGF2." (PMID 33381388, 2020). "Similar findings were observed for esophageal squamous cell carcinoma (ESCC), highlighting the crucial role of FGF-2-mediated activation of the FGF/Erk signaling pathway in maintaining the CSCs." (PMID 41154409, 2025). "The FGF2-mediated FGFR/ERK pathway was previously considered to regulate CSCs, and inhibition of this signaling could delay tumor growth in esophageal squamous cell carcinoma." (PMID 31801598, 2019). "FGF2 and FGFR3 may be used as prognostic markers of esophageal squamous cell carcinoma." (PMID 33381388, 2020). "In this study, the immunohistochemistry of FGF2, FGFR3, and FGFBP1 was used to further verify the expression of the three proteins in 172 patients with esophageal squamous cell carcinoma (ESCC) who had not received preoperative chemoradiotherapy and its effect on the prognosis of ESCC." (PMID 33381388, 2020).
glomerulosclerosis (7 papers, 2013 to 2025). A hardening of the kidney glomerulus caused by scarring of the blood vessels. "Increased FGF2 levels also confirm its involvement in causing interstitial fibrosis and glomerulosclerosis." (PMID 40514411, 2025). "In agreement with this notion, daily injections of FGF-2 to normal rats or monkeys for up to 60-120 days caused podocyte injury and glomerulosclerosis." (PMID 34308967, 2021). "Renal histological samples were submitted to periodic acid-Schiff and Masson’s Trichrome staining to analyze glomerular density, morphometry of glomerular components and glomerulosclerosis; and to immunohistochemistry for fibroblast growth factor-2 (FGF-2)." (PMID 37851784, 2023). "In another study we showed that upon renal transplantation, vascular and glomerular heparan sulfates convert into profibrotic glycans that bind FGF2 and contribute to glomerulosclerosis and neointima formation." (PMID 28594849, 2017). "This could explain our findings, since the mesangial changes, the accumulation of collagen fibers and high FGF-2 expression were accompanied by marked glomerulosclerosis and a decrease in glomerular density in the WT group, which was partially reversed by 2% L-glutamine supplementation." (PMID 37851784, 2023). "Fibroblast growth factor 2 (FGF2) augments podocyte injury, which induces glomerulosclerosis, although the mechanisms remain obscure." (PMID 34309730, 2021).
infantile hemangiomas (7 papers, 2014 to 2025). "Our findings suggest that NGBR was a promising therapeutic target for attenuating RAS signaling in infantile hemangioma induced by concurrent RTK growth factors, such as EGF, FGF2, and VEGF." (PMID 33400686, 2021).
limb ischemia (7 papers, 2012 to 2025). A ischemia that involves the limb. "Taken together, our data strongly suggest that FECS-Ad generated by a unique FGF2-immobilized substrate might effectively ameliorate critical limb ischemia in a mouse model by promoting various angiogenic factors." (PMID 34408157, 2021).
oral squamous cell carcinoma (7 papers, 2015 to 2025). "Meanwhile, miRNA-23a-3p suppresses cell proliferation in oral squamous cell carcinoma by targeting FGF2 and correlates with a better prognosis." (PMID 40282476, 2025). "High levels of vascular endothelial growth factor (VEGF), fibroblast growth factor (FGF)-2 and angiopoietin (ANG)-2 are found in tissues from oral squamous cell carcinoma (OSCC) and oral potentially malignant disorders (OPMDs)." (PMID 39120324, 2024). "We observed expression of FGF-2 and its receptors FGFR-2 and FGFR-3 in neoplastic progression from normal through stages of epithelial dysplasia to oral squamous cell carcinoma." (PMID 26465941, 2015). "Previous study indicated that ED-71 could suppress oral squamous cell carcinoma by inhibiting HBp17/FGFBP-1, FGF-2, CD31, Ki-67, and Cyp24A1." (PMID 33336024, 2020).
osteonecrosis (7 papers, 2019 to 2024). A none disease characterized by death of bone tissue due to a lack of blood supply. "We have previously reported the efficacy of gelatin hydrogel containing injectable FGF-2 for the regenerative treatment of osteonecrosis of the femoral head." (PMID 31660090, 2019). "Moreover, overexpression of FGF2 delayed the progression of DEX-induced osteonecrosis of the femoral head (ONFH) animal model by regulation PI3K/Akt signaling pathway." (PMID 34663382, 2021). "The increase in FGF-2 expression was observed to suppress TNF-α, a pro-inflammatory cytokine, thereby improving bone regeneration in a model of steroid-induced osteonecrosis." (PMID 39051378, 2024). "In particular, bFGF, also known as FGF-2, has been used for the clinical regenerative treatment of osteonecrosis of the femoral head, demonstrating its safety and efficacy." (PMID 33335895, 2020).
periodontal disease (7 papers, 2016 to 2023). "Recently, fibroblast growth factor-2 (FGF-2) agents for periodontal tissue regeneration have been increasingly applied to the treatment of periodontal disease." (PMID 36159352, 2022). "The use of FGF-2 represents a new direction in the treatment of periodontal disease." (PMID 36159352, 2022). "Under this condition, FGF-2 promoted an increase in alveolar bone, cementum, and PDL in a Beagle dog 2-wall periodontal defect model as well as in various animal models of periodontal diseases." (PMID 27391131, 2016).
peripheral artery disease (7 papers, 2014 to 2024). "Finally, the clinical usage of SeV is limited, including a phase I clinical trial with a SeV vector expressing the human fibroblast growth factor-2 (FGF-2) gene to treat peripheral arterial disease." (PMID 25889591, 2015). "Also, F/P MPs promoted collateral vessel formation in peripheral artery disease (PAD) models when applied with FGF-2." (PMID 24995338, 2014).
pituitary adenomas (7 papers, 2008 to 2020). "The overexpression of fibroblast growth factor receptor 1 (FGFR1), a receptor of FGF-2, is also closely related to the invasiveness of pituitary adenomas." (PMID 30733705, 2019). "The PTTG is abundantly expressed in pituitary adenomas and various other tumors types and is known to stimulate fibroblast growth factor-2 (FGF-2)." (PMID 29615979, 2018). "The 18 kDa FGF2 isoform is highly expressed in the normal human pituitary, while pituitary adenomas produce predominantly the 24 kDa form." (PMID 25505910, 2014). "FGF2 is also expressed by human pituitary adenoma cells in vitro, and high levels of serum FGF2 were found in patients bearing pituitary tumors, declining following surgical adenomectomy." (PMID 25505910, 2014). "Pituitary adenomas may over-express certain growth factors or their receptors such as FGF-2, EGF, TGF-α, EGF-R, Notch-3, FGF-R1, and VEGF." (PMID 18081553, 2008). "PTTG stimulates fibroblast growth factor 2 (FGF2) and VEGF production, thus further promoting the invasiveness and angiogenesis of pituitary adenomas, especially prolactinoma and growth-hormone-secreting adenomas." (PMID 32188093, 2020). "For example, VEGF, FGF-2, FGFR1, and PTTG, which give a particular vascular phenotype, are modified in human and experimental pituitary adenomas of different histotypes." (PMID 25505910, 2014). "Pituitary tumors have been shown to express FGF2; GFG protein levels are higher in the normal gland than in most tumors, and aggressive pituitary adenomas appear to express more FGF-2 than GFG mRNA." (PMID 25505910, 2014). "All these findings elucidated that PTTG, FGF-2, and VEGF might act in synergy from the early development to increase the invasiveness and angiogenesis of pituitary adenomas, especially prolactinoma and growth hormone–secreting adenomas." (PMID 30733705, 2019). "The study pointed out that hypoxia-inducible factor-1α, pituitary tumor transforming gene, vascular endothelial growth factor, fibroblast growth factor-2, and matrix metalloproteinases (MMPs, mainly MMP-2, and MMP-9) are core molecules responsible for the invasiveness of pituitary adenomas." (PMID 30733705, 2019).
vitiligo (7 papers, 2022 to 2025). Generalized well circumscribed patches of leukoderma that are generally distributed over symmetric body locations and is due to autoimmune destruction of melanocytes. "Incidentally, FGF-2 is already used in clinics for vitiligo treatment." (PMID 40004167, 2025). "Indeed, patients with vitiligo express a lower level of FGF-2 mRNA." (PMID 40004167, 2025).
AIDS (6 papers, 2011 to 2024). A syndrome resulting from the acquired deficiency of cellular immunity caused by the human immunodeficiency virus (HIV). "Previous studies suggest that the HIV-1 protein Tat and Fibroblast Growth Factor 2 (FGF-2) have synergistic angiogenic effects in AIDS-KS tumors." (PMID 25429350, 2014). "In this study, we have described a potential novel mechanism by which the release and activity of FGF-2 can be modulated in AIDS-KS lesions." (PMID 25429350, 2014). "Since FGF-2 was detected in samples of both classic KS and AIDS-KS and is considered to play an important role in the pathogenesis of AIDS-KS, we explored whether BP1 is expressed in AIDS-KS tumors." (PMID 25429350, 2014). "Raising the concentration of fetal bovine serum increased the secretion of FGF2 from AIDS-KS cells." (PMID 22008609, 2011). "Since either Tat or FGF-2 has been shown to modulate Bcl-2 expression by a wide variety of cell types, herein we evaluated the effects of FGF-2 and Tat, alone or combined, on Bcl-2 expression in animal and in vitro experimental models previously employed to study AIDS-KS pathogenesis." (PMID 22007303, 2011). "FGF-2 also synergizes with the HIV-1 protein Tat to promote angiogenesis and tumor growth in AIDS-KS lesions and Tat has been shown to be able to induce angiogenesis." (PMID 25429350, 2014). "Here, we evaluated whether FGF-2 or HIV-1 Tat, two key AIDS-KS pathogenetic factors, could affect Bcl-2 expression in vivo and in vitro." (PMID 22007303, 2011). "Thus, we carried out this study to determine whether BP1 is expressed in KS lesions, and to define whether BP1, FGF-2, and HIV-Tat have significant protein-protein interactions that could play a potential clinically role in the pathogenesis of AIDS-KS." (PMID 25429350, 2014).
astrocytoma (6 papers, 2000 to 2022). "The genes CDH2, DDB2, DSP, EPO, FGF2, and TEK were overexpressed in an astrocytoma cell line." (PMID 36142793, 2022).
Crohn disease (6 papers, 2010 to 2023). A gastrointestinal disorder characterized by chronic inflammation involving all layers of the intestinal wall, noncaseating granulomas affecting the intestinal wall and regional lymph nodes, and transmural fibrosis. "After verifying COL1A1, CXCL10, MMP2 and FGF2 in samples from CD patients, to further verify the expression of these four genes in Crohn’s disease fibrosis, we prepared a rat model of CD fibrosis using TNBS." (PMID 37622114, 2023).
diabetic nephropathy (6 papers, 2012 to 2024). "Heparanase-1, an endoglycosidase that cleaves heparan sulfate, is implicated in the pathogenesis of diabetic nephropathy and is necessary to FGF-2 for the induction of tubular cells transition." (PMID 23095131, 2012).
Hydrocephalus (6 papers, 2006 to 2025). Hydrocephalus is an active distension of the ventricular system of the brain resulting from inadequate passage of CSF from its point of production within the cerebral ventricles to its point of absorption into the systemic circulation. "Elevated CSF concentrations of fibroblast growth factor (FGF-2) are associated with hydrocephalus and when FGF-2 is introduced into the ventricular system of rats, CSF formation rate declines and CSF outflow resistance increases." (PMID 20181144, 2010). "They successfully induced communicating hydrocephalus by continuously injecting hyperosmolar solutions of dextrans and fibroblast growth factor-2 (FGF-2) into the lateral ventricle for 12 days." (PMID 39908266, 2025). "Group V FGF-2-infused animals had significant hydrocephalus compared to Group I (mean (SD) 42.4 (1.5) vs 23.6 (8.6) μL; p = 0.04)." (PMID 20003330, 2009). "Injection of Fgf2 into the ventricles of the brain, however, has been reported to induce hydrocephalus." (PMID 19114013, 2008). "In a rat model of FGF-2-induced hydrocephalus, both decreased CSF production and increased fibrosis of the CSF absorption pathways were demonstrated." (PMID 16737542, 2006). "Group II (FGF2), group III (10 KD) and group IV (40 KD) animals exhibited significant enlargement of the ventricles (hydrocephalus) compared to group I (I vs II p = 0.002, I vs III p = 0.009, and I vs IV p = 0.023)." (PMID 20003330, 2009).
ischemia reperfusion injury (6 papers, 2020 to 2025). Adverse functional, metabolic, or structural changes in ischemic tissues resulting from the restoration of blood flow to the tissue (reperfusion), including swelling; hemorrhage; necrosis; and damage from free radicals. "Similar trends have been reported in ischemia-reperfusion injury and acute kidney injury models, where exogenous FGF2 administration attenuated renal damage and protected against apoptosis of renal tubular epithelial cells." (PMID 40585885, 2025). "FGFR1 and FGFR2 DKO mice, which exhibit endothelial cell-specific disruption of FGF2 function, have been shown to have significantly worsened cardiac function than controls after ischemia-reperfusion injury as well as significantly decreased vessel density." (PMID 34262947, 2021).
metastatic carcinoma (6 papers, 1997 to 2021). A carcinoma which has spread from the original site of growth to another anatomic site. "Abnormally high concentrations of FGF2 have been found in the serum of patients with active metastatic cancers and these have been shown to correlate significantly with extent of disease, clinical status and mortality risk." (PMID 33573134, 2021). "Perlecan has been identified as a potential therapeutic target for the treatment of metastatic cancer because it is a necessary molecule for tumor vessels' structural integrity and forms the major storage site of neovascularization factor FGF-2." (PMID 20338038, 2010). "Pathways shared by hESCs and metastatic cancers corroborated with our hypothesis that FGF2 regulates self-renewal via TGF-β modulation." (PMID 31758153, 2019).
metastatic melanoma (6 papers, 2013 to 2024). A melanoma that has spread from its primary site to another anatomic site. "The results showed that peginterferon alpha-2b suppressed FGF2 levels in 97% of patients with metastatic melanoma to reference range with a median progression free survival (PFS) and overall survival (OS) of 2.0 and 9.7 months, respectively." (PMID 27007053, 2016). "A phase II clinical study was conducted to evaluate the efficacy of pegintron (peginterferon alpha-2b) in patients with stage IV metastatic melanoma overexpressing FGF2." (PMID 27007053, 2016). "Furthermore, using this chaperone, we revealed a link between the UPR and fibroblast growth factors, as FGF1 and FGF2 are up-regulated in metastatic melanoma cells and can be reduced after 4-PBA treatment." (PMID 29235576, 2017).
Osteopenia (6 papers, 2017 to 2025). Osteopenia is a term to define bone density that is not normal but also not as low as osteoporosis. "Overexpression of FGF2 in mice resulted in shortened long bones along with defective mineralization and osteopenia, suggesting that the gene acts as a negative regulator of bone formation." (PMID 35980984, 2022). "FGF2-null mice exhibit osteopenia and reduced bone remodeling." (PMID 40630222, 2025). "Furthermore, fgf-2 haploinsufficient mice are characterized by generalized osteopenia and fgf-2 knockout mice display greatly reduced trabecular plate-like structures and loss of connecting rods." (PMID 33920587, 2021). "In contrast, non-specific overexpression of FGF2 (Tg-FGF2) in mice exhibits a dwarf phenotype with impaired bone mineralization and osteopenia." (PMID 29259709, 2017).